APOE (apolipoprotein E)
Diseases named in the same sentence as APOE in open-access papers (continued):
Sharing a sentence is not in itself a finding about the gene and the disease.
depression (continued). "We used APOE e4 allele status to predict longitudinal change in depressive symptom scores and risk of depression (defined by a symptom score threshold or use of depression-related medication)." (PMID 33648619, 2021). "Previous results have been mixed regarding the role of the apolipoprotein E e4 (APOE e4) allele in later-life depression: some studies note that carriers experience greater symptoms and increased risk while others find no such association." (PMID 33648619, 2021). "There is evidence that some neuropsychiatric symptoms (e.g., depression, anxiety, apathy, agitation, aggression, hallucinations, and delusions) in AD patients are associated with the ApoE ε4 allele." (PMID 34930329, 2021). "Despite this, there have been relatively few attempts to examine the role of APOE e4 status in depression risk prospectively and among population-based samples." (PMID 33648619, 2021). "In the current study, we demonstrated the potential role of the APOE ε4 allele in the development of depression during aging, which provides substantial evidence for the clinical relationship between APOE ε4 allele and late life depression (LLD)." (PMID 34611141, 2021). "When examining depression risk derived from the HADS Depression score cut-off, individuals with the APOE e4 allele were marginally less likely to experience depression over the follow-up period." (PMID 33648619, 2021). "The current study is one of the largest longitudinal assessments of the role of APOE e4 in later-life depression symptomology and risk." (PMID 33648619, 2021). "We examined the association between APOE e4 allele status and longitudinal change in depressive symptoms and depression risk in later-life, over a 12-year follow-up period." (PMID 33648619, 2021). "Statistical adjustments were made for multiple important confounding factors such as NESB, cardiovascular risk factors, depression, smoking status, physical activity and APOE ɛ4 genotype." (PMID 34733498, 2021). "ApoE gene polymorphism is related to the occurrence and development of depression, which is one of the potential risk factors for depression." (PMID 33833851, 2021). "Altogether, the results evidence that the APOE ε4 allele increases the sensitivity to depression-like behaviors under aging and stress." (PMID 34611141, 2021). "In conclusion, this is one of the first population-based study that examined the prospective risk of APOE*ε4 for incidental depression and depressive symptomology at 4-, 8- and 12-year follow-up across the lifespan." (PMID 32381152, 2020). "For the 60s cohort, there was marginal evidence that APOE*ε4+ status conferred 4- and 8-year risk increases in depressive symptomology and a 12-year risk of reporting any depression." (PMID 32381152, 2020). "We examined the risk of APOE* ε4 for incident depression and depressive symptomology over a 12-year period across the adult lifespan." (PMID 32381152, 2020). "For the 40s cohort, there was marginal evidence for APOE*ε4+ conferring protection for 4-year risk for any depression status (OR = 0.65 (95% CI 0.41–1.01), P = 0.056) and 8-year risk for depressive symptomology (IRR = 0.92 (95% CI 0.84–1.01), P = 0.066)." (PMID 32381152, 2020). "Meta-analyses of genetic studies reported an association of APOE allele ε2 with major depressive disorder." (PMID 33178131, 2020). "In the 40s cohort, those with 2 APOE*ε4+ alleles reported lower depression symptoms (IRR = 0.70 (95% CI 0.54–0.91), P = 0.009)." (PMID 32381152, 2020). "Analysis of the 4-, 8- and 12-year risk of APOE*ε4+ for depression generally conformed with the earlier analyses over the study period." (PMID 32381152, 2020). "Depressed patients had a higher APOE ε4 allele frequency, the APOE ε4 polymorphism was a risk factor of depression." (PMID 30834074, 2019). "APOE ε4 allele increased the depression risk; depressive patients carrying APOE ε4 allele had more severe depressive symptoms." (PMID 30834074, 2019).
depression (continued). "We performed a meta-analysis of recent studies to assess the relationship between APOE ε4 allele and depression." (PMID 30834074, 2019). "APOE ε4 allele was significantly associated with depression (allele: OR=1.36, 95%CI=1.11-1.66, P=0.003; dominant: OR=1.34, 95%CI=1.06-1.68, P=0.001; recessive: OR= 1.11, 95%CI =0.45-2.76, P=0.82)." (PMID 30834074, 2019). "When other ethnological data are updated in the future, we will further improve our research on the association of APOE ε4 allele and depression." (PMID 30834074, 2019). "In this meta-analysis, an association was detected between APOE ε4 allele and depression in three genetic models (allele model, dominant model, and recessive model)." (PMID 30834074, 2019). "This meta-analysis reviewed the existing eligible studies and examined the association between APOE ε4 allele and depression." (PMID 30834074, 2019). "A total of nine studies that met the inclusion criteria were identified by performing a comprehensive search on the association between APOE polymorphisms and depression." (PMID 30834074, 2019). "All analyses were adjusted for age, gender, education, apolipoprotein E ε4 status, vascular risk score, Hamilton Depression Rating Scale score, and use of sleep medication." (PMID 31511066, 2019). "In contrast a longitudinal study investigating the interplay between depression and APOE status on AD risk, proposes an interactional relationship, as that depression constitutes a risk factor only in ε4 carriers." (PMID 31191441, 2019). "Several biological studies reported that apolipoprotein (APOE) ɛ4 is a major known genetic risk factor that synergistically interacts with depression." (PMID 30123386, 2018). "Three such risk factors are the E4 allele of the apolipoprotein E (APOE) gene, depression and neuroticism." (PMID 29451880, 2018). "Depressive symptoms can increase risk of AD/dementia, but, again, selectively in males, although the APOE ε4 genetic risk factor for AD has been associated with increased incidence of depression before onset of AD, but only in females." (PMID 30147642, 2018). "The human apolipoprotein E (ApoE) gene exists in three major isoforms (coded by ε2, ε3, and ε4), and the ε4 allele has been associated with a greater incidence of both depression and AD." (PMID 28934977, 2017). "Age, depression, gender and the apolipoprotein E (APOE) e4 allele are independently associated with δ." (PMID 28291794, 2017). "Our findings illustrate a possible mechanism involving BDNF–5-HT2A signaling pathways by which ApoE isoforms confer differential risk for depression." (PMID 28934977, 2017). "Consistent with clinical autopsy of patients with depression and depression animal models, which reveal a great loss of GABAergic neurons in the brain, we found that the GABAergic neurons in young ApoE-TR mice were greatly reduced following CUMS intervention." (PMID 27406263, 2016). "Another study showed attenuation of the relationship between loneliness and depression in the presence of a specific apolipoprotein (APOE) allele." (PMID 26843197, 2016). "Risk factors included having a first-degree relative with AD, known carriership of apolipoprotein E (ApoE-ε4) allele, or personal history of major depression." (PMID 24622517, 2014). "Early studies also examined the relationship between depression and molecules implicated in general AD pathology, particularly Aβ and APOE 4, the strongest risk allele for AD." (PMID 25133184, 2014). "Covariates included demographic data, disability, depression, alcohol consumption, physical activity, vascular risk factors, serum creatinine level, vitamin intake, and apolipoprotein E genotype." (PMID 20046406, 2008). "By leveraging ApoE knockout (ApoE−/−) and knockdown (ApoE-KD) mouse models, we demonstrated that ApoE deficiency induced depression-like behaviors, which were closely associated with impaired GABAergic synaptic transmission and down-regulation of ApoE receptors and K+–Cl− cotransporter 2 (KCC2)." (PMID 40530388, 2025).
depression (continued). "Although these studies underscore a strong association between ApoE and depression, the precise molecular mechanisms remain largely unknown." (PMID 40530388, 2025). "Individuals with the APOE ε4 genotype or heavy alcohol consumption may be at particularly high risk, with depression and vascular conditions likely involved." (PMID 41275373, 2025). "Considering the accelerated aging process post-menopause, particularly in females with DM and depression, the protective effect of the APOE E4 allele may be diminished in this group." (PMID 40778276, 2025). "A study suggests that APOE-e4 may be a predictor of heterogeneity in cognitive function, as it is linked to depression." (PMID 39092642, 2024). "Moreover, discrepant reports on population studies have separately evaluated ApoE ε4 allele susceptibility to depression, either with positive associations, additional risks, or no prominent influences on depression." (PMID 38506067, 2024). "Apolipoprotein E4 (ApoE4) is involved in the stress‐response processes and is hypothesized to be a risk factor for depression by means of mitochondrial dysfunction." (PMID 38506067, 2024). "However, the exact mechanism and causal relationship between dysregulated inflammation associated with apolipoprotein E4 (ApoE4) and the pathophysiology of depression are yet to be elucidated." (PMID 38506067, 2024). "Likewise, the ApoE-ε4 allele influences the microglial responses and has been confirmed as a risk factor for both AD and depression." (PMID 38903903, 2024). "The ε4 allele of the APOE gene is associated with a high level of depression." (PMID 37763074, 2023). "For the first time, APOE alleles show increased risks for anxiety and depression in Hispanics." (PMID 37510309, 2023). "Therefore, we focused on investigating a known gene, APOE, associated with AD-related phenotypes and two psychiatric diseases (depression and anxiety) within the U.S. Hispanic population in our current study." (PMID 37510309, 2023). "The ε4 allele of the APOE gene is associated with a high level of depression in our study." (PMID 37763074, 2023). "Similarly, ApoE, activated in Oprm1 positive cells in the striatum during morphine withdrawal, has been implicated in several neuropsychiatric disorders including depression and schizophrenia, which can be co-morbid with substance use disorder." (PMID 36534642, 2022). "However, there were differences observed in education years, HVLT Retention, number of e4 alleles in APOE genotype and depression apart from the tremor score in groups." (PMID 35672669, 2022). "SMC is associated with several biological and environmental markers including depression, old age, sex, education, vascular risk, and apolipoprotein E (APOE) ε4." (PMID 35860302, 2022). "However, there are few prospective, population-based studies of the APOE e4-depression association and fewer that examine depressive symptom trajectory and depression risk longitudinally." (PMID 33648619, 2021). "The current study examines the association between APOE e4 status and both longitudinal change in depression symptom scores and depression risk in the Lothian Birth Cohort 1936, a large and representative sample of older adults with over 12 years of longitudinal follow-up." (PMID 33648619, 2021). "ApoE-TR mice at different ages (3 months, 8 months, 18 months) underwent a series of depression-like behavior tests to investigate whether the APOE ε4 allele is a risk factor of depression." (PMID 34611141, 2021). "Therefore, further studies are needed to confirm the relationship between the APOE ε4 allele and depression." (PMID 34611141, 2021). "In summary, APOE ε4 allele increases the vulnerability to depression during aging and stress." (PMID 34611141, 2021). "The relationship between APOE ε4 allele and depression has long been a research focus." (PMID 34611141, 2021).
depression (continued). "As stress increases the susceptibility to depression, we further investigated whether the APOE ε4 allele may aggravate the susceptibility of mice to stress by subjecting apoE-TR mice to forced swimming test (an acute depression animal model)." (PMID 34611141, 2021). "ApoE is a polymorph protein involved in the transformation and metabolism of lipoproteins, and its gene can regulate many biological functions that have been existed as a risk factor in mental diseases, such as depression." (PMID 33833851, 2021). "APOE has been reported to be associated with susceptibility to depression, and the APOE ε2 allele may be an important protective factor for depression." (PMID 34733192, 2021). "Participants with at least one copy of allele A (Met), along with specific alleles (L/S; 10/12; T/C; and 3/3) of other possible MDD-related genes (5HTTLPR, 5HTTVNTR, HTR2A, and APOE), had an increased risk of developing depression (p = 0.004; OR = 5.99; 95%CI = 1.66‐21.56)." (PMID 34760029, 2021). "Subsequently, comparisons of the remaining 14 GDS items as well as the GDS score were also made between the three APOE groups in order to evaluate whether APOE genotype is systematically associated with depression." (PMID 33074098, 2020). "Importantly, however, we have adjusted our analyses to control for the age-related differences in physical health and other comorbidities including education and gender that are likely to have confounded associations between APOE*ε4 status and depression." (PMID 32381152, 2020). "This might indicate that APOE*ε4 is only associated with depression in the very old and where there is more time for exposure to micro-bleeds and other vascular neuropathology, and for Alzheimer pathology to develop in the critical parts of the cortex." (PMID 32381152, 2020). "This indicated that APOE ε4 genotype associated with severity of depression." (PMID 30834074, 2019). "Collectively, the results of this meta-analysis suggested that APOE ε4 allele might be associated with depression, it determined the severity of depression." (PMID 30834074, 2019). "Some have reported that APOE gene polymorphisms were a risk factor for triggering depression." (PMID 30834074, 2019). "The results shown APOE ε4 allele was associated with depression significantly." (PMID 30834074, 2019). "Additionally, this variant has previously been associated with survival in patients with early stage non-small-cell lung cancer, depression, and baseline hippocampal volume loss in apolipoprotein E genotypeε4 (APOE4)." (PMID 31921313, 2019). "Apolipoprotein E (APOE) included ε2, ε3, and ε4 three alleles might be a susceptibility gene of depression." (PMID 30834074, 2019). "However, studies have reached inconsistent conclusions regarding APOE polymorphism frequencies in subjects with depression." (PMID 30834074, 2019). "AD and DLB share many similar risk factors such as depression, smoking, and the APOE ε4 allele." (PMID 29971140, 2018). "These include carriage of the apolipoprotein E ɛ4 allele and mood disorders, including posttraumatic stress disorder, bipolar disorder, major depression, and anxiety." (PMID 29568674, 2018). "Recent research has investigated whether APOE genotype moderates the associations of depression and neuroticism with cognitive ability and decline such that they are stronger in E4 allele carriers." (PMID 29451880, 2018). "Effects of genetic test results are comparable to those described for cardiovascular diseases, since distress anxiety and depression are below clinically significant thresholds, even for gene carriers, and these results concern both APOE and autosomal dominant mutation testing." (PMID 30619456, 2018). "On the basis of the literature and our own work, we hypothesize that the three ApoE isoforms differentially modulate neurotrophic and serotonergic pathways implicated in the pathophysiology of depression." (PMID 28934977, 2017).
depression (continued). "Age, depression, and the apolipoprotein E (APOE) e4 allele are independently associated with δ." (PMID 28291794, 2017). "The goal of this study was to elucidate the mechanisms that underlie the association between the ApoE genotype and depression by examining the three ApoE isoforms’ differential modulation of brain-derived neurotrophic factor (BDNF) signaling, serotonergic signaling, and synaptic function." (PMID 28934977, 2017). "The data provide a probable mechanistic rationale for the differential risk of depression associated with ApoE genetic variants, in which ERβ might play a role." (PMID 28934977, 2017). "In addition to contributing significantly to AD risk, ApoE has been implicated in the etiology of depressive disorders." (PMID 28934977, 2017). "Because late-life depressive symptoms could be a part of the preclinical course of AD, the APOE-ε4 allele may contribute to depression in old age." (PMID 25630472, 2015). "Consistent with a previous study that found increased levels of stress to be associated with increased levels of depression only in APOE-ε4 carriers, we found that the risk of depressive symptoms related to childhood adversity increased with the presence of the APOE-ε4 allele." (PMID 25630472, 2015). "Future investigations are needed to determine whether the 5-HTTLPR s allele and APOE ɛ4 allele interact to contribute to impaired memory function in older adults with depression." (PMID 26393485, 2015). "Hence, has-miR-107 might represent one of the potential underlying mechanisms linking APOE e4 with depression and AD." (PMID 38473892, 2024). "However, APOE-ε3 was associated with depression (p = 0.002) in the Hispanic population." (PMID 37510309, 2023). "In addition, studies on the association between the ApoE gene and depression and antidepressant efficacy have focused on the common alleles of this gene, ε2, ε3, and ε4, and some studies confirmed that the ApoE gene ε4 allele was associated with greater efficacy of antidepressants." (PMID 32795354, 2020). "APOE gene polymorphism status is hypothesized to be a risk factor for depression." (PMID 30834074, 2019). "Finally, the presence of the APOE 4 allele increased depression in women with AD by 4-fold." (PMID 25133184, 2014). "Higher levels of plasma GFAP have been demonstrated both among APOE ε4 carriers and in individuals with depression." (PMID 41476029, 2026). "Lastly, treatment with KCC2 activators, CLP290 and CLP257, restored the expression levels of KCC2 and the GABAAR α1 subunit, significantly alleviating depression-like behaviors induced by CSDS or ApoE-KD." (PMID 40530388, 2025). "Overall, our findings provide new insights into the function of ApoE in the pathophysiology of depression and shed light on developing new interventions." (PMID 40530388, 2025). "To further elucidate its cell-specific mechanism, in subsequent studies, we will employ a hippocampal astrocyte conditional ApoE knockout mouse model to investigate the regulatory role of astrocyte-derived ApoE in the pathophysiology of depression." (PMID 40530388, 2025). "In this study, we employed chronic social defeat stress (CSDS) to establish a mouse model of depression and observed significantly reduced ApoE expression in the hippocampus." (PMID 40530388, 2025). "Lastly, a sensitivity analysis to identify potential interactions amongst apathy, APOE ε4 status and depression medications on conversion rate was conducted." (PMID 40227643, 2025). "Follow‐up logistic regression analyses adjusted for confounders showed a significant interaction between AD concerns and APOE ε4 for depression." (PMID 40476544, 2025). "To further explore the role of ApoE in depression, we engineered an adeno-associated virus (AAV) vector designed to overexpress ApoE (ApoE-OE)." (PMID 40530388, 2025).